MALAT1 (metastasis associated lung adenocarcinoma transcript 1)
Diseases named in the same sentence as MALAT1 in open-access papers (continued):
Sharing a sentence is not in itself a finding about the gene and the disease.
lung cancer (continued). "Notably, high levels of MALAT1 confer resistance to pharmacological treatment, such as cisplatin in lung cancer, while, in ovarian cancer MALAT1 interferes with the Notch pathway, conferring chemo-resistance." (PMID 33375130, 2020). "Studies have confirmed that MALAT1 functions in liver and lung cancer through miRNA-204-5p." (PMID 32993558, 2020). "Since SOX9 is known as a TF and former report has determined that SOX9 is responsible for the upregulation of lncRNA MALAT1 in lung cancer, we asked whether SOX9 could transcriptionally regulate SOX9‐AS1 expression in HCC." (PMID 31402556, 2019). "Interestingly, MALAT1 is induced by the ERβ, a novel role for this receptor in lung cancer progression in female patients." (PMID 31404273, 2019). "Interestingly, the reduced expression of MALAT1 has been reported in the PBMCs of patients with lung cancer, as well as an increased proportion of MDSCs." (PMID 31404149, 2019). "In addition to lung cancer, Malat1 is known to contribute to metastasis in other common types of cancer including hepatocellular carcinoma and bladder cancer, with evidence that it acts through induction of the epithelial-to-mesenchymal transition." (PMID 31616462, 2019). "Indeed, MALAT-1 targets genes associated with lung cancer metastasis, involved in cell migration, tumor growth and it was suggested that MALAT-1 promotes lung cancer brain metastasis by epithelial to mesenchymal transition (EMT) induction." (PMID 30012957, 2018). "Moreover, cisplatin-resistant A549/DDP cells showed higher MALAT1 expression than cisplatin-sensitive lung cancer cells (A549, H460, H1299 and SPC-A1)." (PMID 29484127, 2018). "Metastasis-associated lung adenocarcinoma transcript 1 (MALAT1), localized in nuclear speckles and highly conserved among mammals, regulates alternative splicing and gene expression through additional splicing-independent mechanisms in lung cancer metastasis." (PMID 29868480, 2018). "Moreover, miR-101-3p mimics and si-MALAT1 transfection enhanced cisplatin-induced apoptosis in the lung cancer cells." (PMID 29484127, 2018). "Therefore, in this study, we investigated the mechanism by which MALAT1 regulates cisplatin resistance in lung cancer." (PMID 29484127, 2018). "Thus, our study indicates that MALAT1 is a potential therapeutic target in cisplatin-resistant lung cancer patients." (PMID 29484127, 2018). "LncRNA MALAT1 is known to reduce metastasis and could serve as a biomarker to predict lung cancer prognosis." (PMID 30086763, 2018). "Furthermore, in the context of DNA methylation, it has been previously reported that lung cancer tissues exhibit reduced methylation in the MALAT1 promoter, which subsequently enhances MALAT1 expression." (PMID 29695738, 2018). "Moreover, lung cancer patients can be distinguished as cisplatin-sensitive or cisplatin-resistant based on MALAT1 expression." (PMID 29484127, 2018). "However, the mechanistic role of MALAT1 in cisplatin-resistance of lung cancer remains poorly understood." (PMID 29484127, 2018). "It had been shown that MALAT1 was upregulated in many cancers and might act as a biomarker to predict survival in lung cancer." (PMID 30069164, 2018). "Next, we investigated if MALAT1 regulated apoptosis of lung cancer cells." (PMID 29484127, 2018). "One good example of its preclinical study proposed that ASO of MALAT1 could inhibit lung cancer metastasis in vivo significantly." (PMID 29368602, 2018). "MALAT1 is one of the most well-characterized and studied lncRNAs in cancer and has been identified as a regulator of metastasis and cell migration, a prognostic marker, and a transcriptional regulator of alternative splicing in lung cancer." (PMID 29757368, 2018). "MALAT1 expression might be regulated by DNA methylation in lung cancer by evaluating methylation status of the CpG island at the MALAT1 promoter." (PMID 30093838, 2018). "High levels of MALAT1 are reported in cisplatin-resistant H460R lung cancer cells." (PMID 29484127, 2018).
lung cancer (continued). "Next, we investigated the effects of MALAT1 knockdown on chemo-sensitivity of lung cancer cells." (PMID 29484127, 2018). "Furthermore, qRT-PCR analysis of lung cancer patient tissues showed that MALAT1 expression negatively correlated with miR-101-3p levels (R = -0.549)." (PMID 29484127, 2018). "The in vitro siRNA-mediated MALAT1 silencing resulted in impaired lung cancer cell motility by altering the expression levels of cell motility-related genes, such as HMMR at pre-mRNA transcriptional level and CTHRC1, CCT4 and ROD1 at post-transcriptional level." (PMID 28253859, 2017). "However, the mechanism by which MALAT1 regulates the chemo-resistance of lung cancer cells to DDP remains to be investigated." (PMID 29212230, 2017). "MALAT1 contributes in metastasis phenotype of human lung cancer cells." (PMID 29632545, 2017). "MALAT1 knockdown in lung cancer cells decreases cell migration abilities." (PMID 28615056, 2017). "In contrast, knockdown of MALAT1 in A549 lung cancer cells decreased proliferation, which is consistent with our results that MALAT1 plays a role in lung cancer cell proliferation and this provides new insight into the role of MALAT1 in various cancer types." (PMID 28615056, 2017). "In the present study, we confirmed a high expression of MALAT1, a well-studied oncogenic lncRNA in lung cancer, is associated with poorer clinicopathologic features, which has inspired us to further investigate the potential role of MALAT1 in chemo-resistance of lung cancer cells." (PMID 29212230, 2017). "Long non-coding RNA MALAT1 enhances brain metastasis by inducing EMT in lung cancer." (PMID 28615992, 2017). "Moreover, NEAT1 and MALAT1 acted as downstream effectors of Oct4 to promote proliferation, migration and invasion abilities of A549 lung cancer cells." (PMID 28615056, 2017). "Consistent with our earlier results, MALAT1 knockdown reduced the lC50 values of lung cancer cells; moreover, miR-101 inhibition significantly promoted the lC50 values, and partially reversed the effect of MALAT1 on lung cancer cell chemo-resistance." (PMID 29212230, 2017). "In addition to the interaction with miR-101, SOX9 binds to the promoter of MALAT1 to promote MALAT1 expression, thereby enhancing the chemo-resistance of lung cancer." (PMID 29212230, 2017). "Since MALAT1 knockdown could amplify the suppressive effect of DDP on lung cancer cell viability; we further investigated the detailed function of MALAT1/miR-101 in regulating the chemo-resistance of lung cancer cell." (PMID 29212230, 2017). "In addition, knockout studies of MALAT1 have demonstrated that in lung cancer, MALAT1 can also directly regulate the expression of pro-metastatic genes." (PMID 29113413, 2017). "We demonstrated the MALAT1-miR-101-SOX9 feedback loop in lung cancer for the first time; this MALAT1-miR-101-SOX9 feedback loop may potentially act as an effective therapeutic candidate combined with traditional DDP-based chemo-therapy for lung cancer." (PMID 29212230, 2017). "The expression of MALAT1 was firstly monitored in lung cancer tissues." (PMID 29212230, 2017). "Moreover, NEAT1 and MALAT1 function as Oct4 downstream mediators to promote lung cancer proliferation, migration and invasion." (PMID 28615056, 2017). "MALAT1 was first identified as a prognosis marker in early-stage metastasizing lung cancer." (PMID 28615056, 2017). "MALAT1 acts as a transcriptional regulator controlling expression of a number of genes involved in metastasis and prognosis in a variety of cancers, including lung cancer and in PDAC." (PMID 28957348, 2017). "In addition to lung cancer, MALAT1 has proven itself as a prominent biomarker with its elevated expression detected in plasma and urine of prostate cancer patients, with a sensitivity and specificity of 58.6% and 84.8%, respectively (AUC 0.836)." (PMID 28634418, 2017).
lung cancer (continued). "Long noncoding RNAs (lncRNAs) such as HOTAIR and MALAT1 have been shown to be involved in the development of breast and lung cancer, however, role of lncRNAs in lymphoma is still unknown." (PMID 29113297, 2017). "MALAT1 knockdown could also sensitized DDP-resistant lung cancer cells (A549/DDP and H1299/DDP) to DDP." (PMID 29212230, 2017). "However, the mechanism by which MALAT1 affects the chemo-sensitivity of lung cancer cells remains to be investigated." (PMID 29212230, 2017). "In addition, knockdown of NEAT1 or MALAT1 abolished Oct4-mediated lung cancer cell growth and motility." (PMID 28615056, 2017). "Previous studies prove that MALAT1 promotes migration, metastasis and proliferation of lung cancer." (PMID 28938549, 2017). "The study by Shen showed that increased levels of long non-coding RNA metastasis-associated lung adenocarcinoma transcript 1 (MALAT1) promotes lung cancer brain metastasis by EMT, whereas silencing of MALAT1 inhibits lung cancer cell migration and metastasis in the brain." (PMID 27018053, 2016). "MALAT1 is overexpressed in lung cancer, GC, and cervical cancer." (PMID 27835600, 2016). "Involvement of MALAT1 in cancer metastasis was first reported in the case of non-small cell lung cancer patients, where overexpression of MALAT1 was positively correlated with lung cancer metastasis." (PMID 27250026, 2016). "Gene expression of MALAT1 is critical for lung cancer metastasis." (PMID 27018053, 2016). "Aside from HOTAIR and MALAT1, several other lncRNAs are correlated with lung cancer metastasis." (PMID 27686732, 2016). "Additional studies found that MALAT1 could regulate gene expression, especially for those that are involved in lung cancer cell migration, metastasis, and colony formation." (PMID 27713484, 2016). "Lastly, long non‐coding RNAs could be exploited therapeutically, as well, for example, suppression of the lncRNA MALAT1 in lung cancer metastasis." (PMID 26992833, 2016). "Several characterized cancer-associated lncRNAs were identified, such as PVT1, TINCR, and GAS5; while the well-known lung cancer-associated lncRNA, MALAT1 was not included." (PMID 26918601, 2016). "MALAT-1 promotes metastasis and serves as a prognostic indicator in lung cancer." (PMID 27095571, 2016). "All these indicated that MALAT1 could be an effective therapeutic target in lung cancer in the future." (PMID 27143813, 2016). "Further studies evaluated the role of MALAT1 in the regulation of motility-related genes and metastasis phenotype in lung cancer cells, definitively establishing its role in the processes of cell migration and metastasis, also defining a more malignant neoplastic phenotype." (PMID 25593996, 2014). "The maturation of SPRY4-IT1 is similar to the nuclear processing of MALAT1 in lung cancer." (PMID 25344859, 2014). "Additionally, recent studies show that MALAT1 induces liver and colorectal cancer cell migration and invasion in vitro, and induces lung cancer cell migration, invasion and metastasis in vitro and in vivo." (PMID 24742640, 2014). "Because of its low sensibility and high specificity, MALAT1 detection in blood samples might be used as a complementary biomarker within a panel to improve lung cancer diagnosis." (PMID 25593996, 2014). "In addition to its role in regulating lung cancer metastasis, MALAT1 is upregulated in uterine endometrial stromal sarcoma, cervical cancer and hepatocellular carcinoma, while its expression in the corresponding healthy tissues is undetectable or intermediate." (PMID 24013378, 2013). "We also performed xenograft tumor experiments with MALAT1 knockdown A549 lung cancer cells." (PMID 23717670, 2013). "Moreover, MALAT1 affects the stability and transport of specific mRNAs related to cell migration and invasion, enhancing their stability and thereby regulating the biological behavior of lung cancer cells." (PMID 41394878, 2025).
lung cancer (continued). "Since upregulation of MALAT1 is associated with an elevated level of MCP-1 in plasma of AA lung cancer patients, we broadened our study to analyze MALAT1 and MCP-1 in lung tumor tissues and adjacent non-cancerous lung tissues of 46 NSCLC patients, including 23 AAs and 23 WAs." (PMID 38791954, 2024). "Additionally, it was shown that lung cancer patient PBMCs had lower MALAT-1 levels." (PMID 38511067, 2024). "Similarly, lncRNA MALAT1 has been implicated in COPD pathogenesis and lung cancer metastasis." (PMID 39201688, 2024). "However, MALAT1 in both lung cancer tissue types was significantly lower than in normal tissue." (PMID 39725668, 2024). "Evidence shows that Metastasis-associated lung adenocarcinoma transcript 1 (MALAT1, also called nuclear enriched abundant transcript 2 or NEAT2), an lncRNA highly abundant in lung tissues, is implicated in the pathogenesis of chronic lung diseases, including both COPD and lung cancer." (PMID 36769181, 2023). "Thus, MALAT1 is a putative drug target for the treatment of several different types of lung cancer." (PMID 36419933, 2022). "In addition, knockout MALAT1 inhibited OCT4-mediated lung cancer cell growth." (PMID 36420141, 2022). "In summary, MALAT1 plays an important role in the development and progression of lung cancer through multiple mechanisms and thus may serve as a potential biomarker and target for treatment of lung cancer." (PMID 34976181, 2022). "In addition, restricting MALAT1 activity at cellular level could result in improvement in the promotion of apoptosis and prevent migration and invasion of paclitaxel-resistant lung cancer cells." (PMID 35281907, 2022). "Moreover, the same investigators achieved functional knockout of MALAT1 through zinc finger nuclease (ZFN)-mediated site-specific integration of RNA destabilizing elements into the human genome, which showed efficient silencing of the highly abundant MALAT1 in human lung cancer cells." (PMID 34778078, 2021). "Similarly, MALAT1 was reported to be induced in hypoxia and to regulate polypyrimidine tract-binding protein (PTB)-associated splicing factor transcriptionally in A549 lung cancer cells." (PMID 34012919, 2021). "Therefore, we hypothesized that MALAT1 may act as a ceRNA to modulate UBE2C expression in regulating lung carcinoma progression." (PMID 34257576, 2021). "We speculated that UBE2C is involved in lung carcinoma progression, which is regulated by MALAT1." (PMID 34257576, 2021). "Also, targeting MALAT1 by ASO can inhibit metastasis in a lung cancer xenograft model." (PMID 32122355, 2020). "A recent research noticed the proportion of MDSCs in patients with lung cancer, the amount of ARG-1 in MDSCs, and the CD8+CTL cells percentage, and they also examined the MALAT1 association with MDSCs in PBMCs and revealed the regulatory activity of MALAT1 on MDSCs stimulation in vitro." (PMID 33133086, 2020). "Furthermore, the combined positive likelihood ratio suggested that the probability of positive expression of MALAT1 in lung cancer patients was 2.6 times higher than that in the control group, which further reflected the potential value of circulating MALAT1 in the diagnosis of lung cancer." (PMID 31846184, 2020). "Finally, metastasis-associated lung adenocarcinoma transcript 1 (MALAT-1), is on 11q13 and transcribed from the nuclear-enriched transcript 2 (NEAT2), which has been identified as a prognostic factor in patients with stage I lung cancer." (PMID 31632922, 2019). "However, levels of MALAT1 are elevated in NSCLC, which suggests MALAT1 and/or miR-155 do not play a significant role in FBXW7 regulation and implies that the MALAT1/miR-155/FBXW7 axis may have a tumor suppressor role in lung cancer." (PMID 30086763, 2018). "Malat1 loss of function in mouse revealed that it is a nonessential gene in development or for adult normal tissue homeostasis, but depletion of MALAT1 in lung carcinoma cells impairs cellular motility in vitro and metastasis in mice." (PMID 29641489, 2018).
lung cancer (continued). "However, MALAT1-promoting lung cancer cell proliferation in different studies are contradictory." (PMID 28615056, 2017). "However, whether MALAT1 is involved in the chemo-resistance of lung cancer cell still remains unclear." (PMID 29212230, 2017). "Overexpression of metastasis-associated lung adenocarcinoma transcript 1 (MALAT1), SBF2 antisense RNA 1 (SBF2-AS1), and Homo sapiens TatD DNase domain containing 1 (TATDN1) is capable of enhancing the ability of proliferation, metastasis, and invasion of lung cancer." (PMID 27589728, 2016). "Additionally, it was suggested that MALAT1 might also regulate other important cellular processes in lung cancer." (PMID 24313945, 2013). "Aberrant expression of certain lncRNAs in lung cancer cells, such as HOTAIR, MALAT1, and HOTTIP, is closely related to TNM stage, lymph node metastasis, and survival rate." (PMID 40746614, 2025). "Interestingly, MALAT1 appears to mediate its major functions through altering the expression of many genes involved in oncogenic signalling pathways in lung cancer rather than modulating alternative splicing, especially in early‐stage lung cancer that eventually metastasize." (PMID 40783798, 2025). "For instance, in a lung cancer xenograft animal model, LNP-encapsulated ASOs targeting nuclear lncRNA MALAT1 demonstrated significant inhibition of tumor metastasis and notable therapeutic efficacy." (PMID 37702834, 2025). "Recently, in a xenograft lung cancer mouse model, the application of ASO–Au–TAT nanoparticles (NPs) targeting the nuclear lncRNA MALAT1 significantly inhibited tumor metastasis and extended the survival time of mice by 80%." (PMID 40584410, 2025). "MALAT1 interacts with splicing regulators such as RBFOX2 and promotes epithelial-to-mesenchymal transition in ovarian and lung cancers, highlighting a targetable vulnerability in metastatic progression." (PMID 40861865, 2025). "This study aims to combine the understanding of the role of MALAT1, HOTAIR, and AFAP1‐AS1 lncRNAs in the metastasis of lung cancer by pulling the findings of the previous studies." (PMID 39725668, 2024). "LncRNAs, including MALAT1, H19, and NEAT1, have been suggested to predict patient outcomes in lung cancer more precisely." (PMID 39325172, 2024). "In lung cancer, METTL3 overexpression facilitates drug resistance and metastasis by promoting the translation of YAP and MALAT1 transcripts in cooperation with YTHDF1/3 reader proteins." (PMID 38966069, 2024). "Here we observe a rise in MALAT1 expression, correlating with increased levels of MCP-1 and CD68, CD163, CD206, indicative of M2 macrophages in tumor tissues of AA lung cancer patents." (PMID 38791954, 2024). "MALAT1 expression is upregulated in COPD and lung cancer tissues, where it promotes tumor invasion and metastasis by regulating alternative splicing events and gene expression programs associated with metastatic progression." (PMID 39201688, 2024). "MALAT1 and PVT1 levels were mostly higher in AA lung cancer patients, while RMRP was notably elevated in WA lung cancer patients (all p < 0.05)." (PMID 38791954, 2024). "A collective lncRNAs exhibited aberrant expression levels in tumors when compared to their paired normal tissues, such as MALAT1, H19, and MEG3, displayed differential expression across all stages of lung cancer formation." (PMID 38270295, 2024). "Liu and colleagues demonstrated that MALAT1 is up-regulated in NSCLC tissues with bone metastasis and in lung cancer cell lines with high bone metastatic tropism." (PMID 37143733, 2023). "Metastase-associated lung adenocarcinoma transcription 1 (MALAT1), also known as NEAT2, is an 8 KNT long non-coding RNA (IncRNA) located on 11q13 and was originally considered as a poor prognostic parameter for lung cancer patients." (PMID 37873058, 2023).